NOLC1 (nucleolar and coiled-body phosphoprotein 1)
Diseases named in the same sentence as NOLC1 in open-access papers (continued):
Sharing a sentence is not in itself a finding about the gene and the disease.
non-small cell lung carcinoma (2 papers, 2018 to 2025). A group of at least three distinct histological types of lung cancer, including non-small cell squamous cell carcinoma, adenocarcinoma, and large cell carcinoma. "Previous studies have shown that the expression of NOLC1 increases in non-small cell lung cancer, promoting multidrug resistance (MDR), and that its downregulation sensitizes MDR cells." (PMID 41227344, 2025).
Anxiety (1 paper, 2023). Intense feelings of nervousness, tension, or panic often arise in response to interpersonal stresses. "Of the 11 gene scores in the anxiety symptom group, we replicated six genes, including CNNM2, EXD3, GBF1, NT5C2, NOLC1 and TRIM." (PMID 37322117, 2023).
breast invasive carcinoma (1 paper, 2022). "NOLC1 expression was significantly higher in breast invasive carcinoma (BRCA) compared with adjacent normal tissues." (PMID 35174077, 2022).
colorectal cancer (1 paper, 2023). A primary or metastatic malignant neoplasm that affects the colon or rectum. "NOLC1, as an independent risk factor affecting the prognosis of colorectal cancer patients, can lead to a poor prognosis of colorectal cancer." (PMID 37670166, 2023). "Our results suggest that NOLC1 is overexpressed in colorectal cancer, and that overexpression of NOLC1 is associated with relevant clinical features." (PMID 37670166, 2023). "To identify potential therapeutic targets for colorectal cancer and improve its prognosis, we analyzed the relationship between NOLC1 expression level and drugs based on the GDSC database, and the corresponding parameters are shown." (PMID 37670166, 2023). "Further studies and clinical trials are needed to confirm the role of NOLC1 in the development and progression of colorectal cancer." (PMID 37670166, 2023). "We also established a survival prediction model related to NOLC1 expression to predict the 2-year, 4-year, and 6-year survival rates of colorectal cancer, providing a basis for clinical diagnosis and treatment improvement." (PMID 37670166, 2023). "High expression of NOLC1 as an independent prognostic factor for survival in patients with colorectal cancer." (PMID 37670166, 2023). "This study further investigated the role of NOLC1 in colorectal cancer tumors, aiming to provide sufficient scientific evidence for the clinical treatment of colorectal cancer." (PMID 37670166, 2023). "Subsequently, KEGG and GO enrichment analysis was used to identify the potential molecular mechanism of NOLC1 promoting the occurrence and development of colorectal cancer." (PMID 37670166, 2023). "From the analysis of the clinical pathology data, we found that the expression level of NOLC1 was correlated with the age of the colorectal cancer patient, post-operative tumor residuals, lymph node invasion, and history of colorectal cancer." (PMID 37670166, 2023). "We conducted an enrichment pathway analysis to further explore the potential role of NOLC1 in the progression of colorectal cancer." (PMID 37670166, 2023). "The K–M survival analysis showed that the higher the expression of NOLC1, the worse the overall survival prognosis of colorectal cancer." (PMID 37670166, 2023). "The influence of NOLC1 expression on the immune microenvironment of colorectal cancer patients was further investigated using the TIMER database." (PMID 37670166, 2023). "Meanwhile, Western Blotting, and IHC staining experiments were performed, and the results also showed that NOLC1 expression was significantly increased in colorectal cancer cells and tissues." (PMID 37670166, 2023). "The results showed that in colorectal cancer, the high expression of NOLC1 was closely related to multiple immune checkpoints, such as LAG3, CTLA-4, and PDCD1LG2, leading to immune tolerance or escape of tumor cells." (PMID 37670166, 2023). "The results showed that the expression of NOLC1 was significantly decreased in colorectal cancer cells after transfection." (PMID 37670166, 2023). "To investigate whether NOLC1 affects the biological function of colorectal cancer cells, we used EdU assay to measure the proliferation capacity of HCT116 and LS174T cells." (PMID 37670166, 2023). "To verify the RNA sequencing results, we used Western blot and immunohistochemistry to confirm the expression of NOLC1 in colorectal cancer cell lines and tissues, and the results confirmed that NOLC1 was overexpressed in colorectal cancer tissues compared with normal colorectal cells and tissues." (PMID 37670166, 2023). "Further analysis was conducted to further explore the role of NOLC1 in colorectal cancer." (PMID 37670166, 2023). "The specific mechanism of NOLC1 regulation of colorectal cancer is still unclear." (PMID 37670166, 2023). "NOLC1 enhances the proliferation and migration of colorectal cancer cells." (PMID 37670166, 2023).
colorectal cancer (continued). "In addition, we further used the LinkedOmics network analysis tool to explore the co-expression of the NOLC1 gene in an attempt to find the potential genes affecting the occurrence and development of colorectal cancer." (PMID 37670166, 2023). "In addition, data provided by the TNMplot database also showed that NOLC1 expression levels were significantly different in colorectal cancer compared with normal tissues (P = 8.5E−1 and 5.6E−31)." (PMID 37670166, 2023). "Therefore, immune checkpoint blocking therapy offers a broad therapeutic prospect for patients with high expression of NOLC1 in advanced colorectal cancer." (PMID 37670166, 2023). "Subsequently, the expression of NOLC1 in colorectal cancer was verified by the TNMplot database." (PMID 37670166, 2023). "In addition, we verified the effect of NOLC1 expression on the migration capacity of colorectal cancer cells." (PMID 37670166, 2023). "We used TCGA, GEO, TNMplot, GEPIA, and other databases to explore the expression level of NOLC1 in colorectal cancer patients, as well as the correlation between the clinical characteristics of colorectal cancer patients and their expression, and conducted the prognostic analysis." (PMID 37670166, 2023). "However, the significance of NOLC1 expression in the prognosis of colorectal cancer remains unclear." (PMID 37670166, 2023). "However, there are few reports on the mechanism of NOLC1 in colorectal cancer." (PMID 37670166, 2023). "Therefore, we hypothesized that NOLC1 plays an indispensable role in the regulation of the occurrence and development of colorectal cancer, and it may promote the invasion and metastasis of colorectal cancer together with MCM10, HELLS, and Noc3L-related genes." (PMID 37670166, 2023). "The results showed that NOLC1 was highly expressed in ACC, BLCA, BRCA, CESC, and other tumor types compared with normal tissues, with statistical significance, and there was a significant difference in colorectal cancer (P = 7.1E−197)." (PMID 37670166, 2023). "In addition, NOLC1 may be associated with MCM10, HELLS, NOC3L, and other genes through participating in Wnt signaling pathways and jointly regulate the occurrence and development of colorectal cancer under the influence of the tumor microenvironment and many other influencing factors." (PMID 37670166, 2023).
epilepsy (1 paper, 2022). A brain disorder characterized by episodes of abnormally increased neuronal discharge resulting in transient episodes of sensory or motor neurological dysfunction, or psychic dysfunction. "As FHFs and NOLC1/TCOF1 are implicated in severe disease, including epilepsy, cancer and ribosomopathy, future studies should aim to decipher the functional interplay between FHF proteins and NOLC1/TCOF1." (PMID 36411431, 2022).
gastric tumors (1 paper, 2023). "Additionally, the gene enrichment analysis suggests the participation of the NOLC1 gene as an important regulator for the development and progression of gastric tumors." (PMID 37765273, 2023).
lentivirus infection (1 paper, 2021). Virus diseases caused by the Lentivirus genus. "In order to further explore the association between NOLC1 and AKT, after NOLC1 overexpression lentivirus infection, the PI3K inhibitor LY294002 (25 μmol/L) was utilized to treat Eca109 and TE-13 cells." (PMID 34046062, 2021).
liver fibrosis (1 paper, 2024). "Downregulated Nolc1 and Clic4 are probably among the most important positive effects of NMN in the liver, as it was previously reported that Nolc1 contributes to the activation of hepatic stellate cells, which are key players in the development of liver fibrosis." (PMID 38473844, 2024).
lymph node metastasis (1 paper, 2021). "NOLC1 overexpression was markedly associated with bigger tumor size, lymph node metastasis, and advanced TNM stage." (PMID 34046062, 2021). "Moreover, NOLC1 overexpression was associated with bigger tumor size, lymph node metastasis, and advanced TNM stage in ESCA patients." (PMID 34046062, 2021).
osteosarcoma (1 paper, 2017). A usually aggressive malignant bone-forming mesenchymal neoplasm, predominantly affecting adolescents and young adults. "qRT–PCR and Western blot analyses demonstrated that CSIG knockdown increased the expression of NOLC1, as well as in human osteosarcoma U2OS and diploid fibroblast 2BS cells." (PMID 28493459, 2017).
Sepsis (1 paper, 2023). Sepsis is defined as life-threatening organ dysfunction caused by a dysregulated host response to infection. "Thus, the expression levels of the eight RBPs (DDX24, CBFA2T2, NOP14, ILF3, DNMT1, FTO, PPRC1, and NOLC1) were altered in the patients with sepsis might potentially be useful as novel biomarkers as well as targets to facilitate the diagnosis and management of sepsis." (PMID 37749550, 2023). "GO analysis of the DE RBPs in sepsis identified terms that were mostly enriched in the immune/inflammatory response; we identified significant differences in 8 down-regulated RBPs in sepsis, including DDX24, CBFA2T2, NOP, ILF3, DNMT1, FTO, PPRC1, NOLC1." (PMID 37749550, 2023).
Stroke (1 paper, 2023). Sudden impairment of blood flow to a part of the brain due to occlusion or rupture of an artery to the brain. "Our research findings highlight the significance of genes associated with the UPR pathway, including ATF6, EXOSC5, EEF2, LSM4, NOLC1, BANF1, and DNAJC3, in the occurrence of stroke." (PMID 37891634, 2023).
viral infection (1 paper, 2017). "This further suggests that the interaction between NOLC1 and NS1 may play an important role in viral infection." (PMID 29212246, 2017).
cancer (22 papers, 2013 to 2025). A tumor composed of atypical neoplastic, often pleomorphic cells that invade other tissues. "The functions of NOLC1 in cancer are controversial, as evidenced by its pro- or antitumor potential in different tumor types and models." (PMID 40864495, 2025). "NOLC1 is upregulated in most cancers and promotes non-small cell lung cancer (NSCLC) resistant to multiple drugs." (PMID 40864495, 2025). "A very similar pattern was observed in the TCGA pan-cancer data set, where NOLC1 was one of the top two genes positively correlated with RCOR1 expression." (PMID 41227344, 2025). "In TCGA data sets, we observed that NOLC1 was among the top genes correlated with RCOR1 expression both in pan-cancer and melanoma patient cohorts." (PMID 41227344, 2025). "To explore the role of NOLC1 in tumor genesis and development, we evaluated the expression of NOLC1 in generalized carcinoma types using TCGA and GTEx data." (PMID 37670166, 2023). "NOLC1 is a cellular target of the anti-cancer drug doxorubicin and natively unfolded scaffold protein that shuttles between the nucleolus and the cytosol, affecting the cellular localization of its binding partners." (PMID 36411431, 2022). "To further evaluate the mRNA expression level of NOLC1 in human cancers, we analyzed NOLC1 expression using the TIMER2.0 database." (PMID 35174077, 2022). "The transcriptional level of NOLC1 shows a positive correlation with the growth rate but this higher expression does not seem to be sufficient to arrest the growth rate of the studied cancer cell lines." (PMID 24154670, 2013). "Recent studies have demonstrated that NOLC1 is upregulated in most cancers." (PMID 40864495, 2025). "Previous studies clarified that NOLC1 plays various roles in different cancers." (PMID 40367575, 2025). "The mRNA expression of NOLC1 in cancer cells, Kyse170, ECA9706, and T.TN is different from the protein expression, which may be due to post-transcriptional regulatory mechanisms such as translation and post-translational modifications." (PMID 34046062, 2021). "Therefore, NOLC1 suppresses cancer progression through various mechanisms in different types of cancers." (PMID 33767130, 2021). "Previous studies showed that gene fusion MAN2A1-FER, Pten-NOLC1 and SLC45A2-AMACR are the cancer drivers." (PMID 34417538, 2021). "From the cross-cancer alteration analysis under the simultaneous query of MYC, NOLC1, DHX33, and CHD7, a large number of cancers possess alterations in these genes." (PMID 27198694, 2016). "The expression and role of NOLC1 in cancer have not been clearly investigated." (PMID 33767130, 2021). "In line with the molecular functions of the selected genes modulating transcription (BPTF, DDX21), protein translation (NOLC1, TCOF1), or nuclear import (KPNA2) it is feasible to speculate that restoring their cellular content in cancer cells could facilitate viral production." (PMID 34203557, 2021).
tumor (18 papers, 2017 to 2025). "NOLC1 overexpression was markedly associated with larger tumor size, lymph node metastases and advanced TNM stage." (PMID 37765273, 2023). "In conclusion, NOLC1 plays a key role in the occurrence and development of various tumors and is expected to play a role as an early tumor diagnostic marker." (PMID 37670166, 2023). "Proteomic analysis of tumors and functional studies of cell cultures established nucleolar and coiled-body phosphoprotein 1 as a key node, whose convergent regulation, both transcriptionally and posttranslationally, is critical for tumor cell proliferation." (PMID 40834066, 2025). "In vivo studies showed that up-regulation of circ-NOLC1 suppressed tumor growth (tumor volume: P < 0.001; tumor weight: P < 0.01)." (PMID 40533863, 2025). "H&E staining revealed the same trend: the NOLC1-knockdown group treated with Cis plus anti-PD-1 presented the most severe necrosis in the tumor tissues." (PMID 40864495, 2025). "The overexpression of circ-NOLC1 in CaSki cells significantly inhibited the tumor growth of CC xenografts in nude mice (tumor volume: reduced by 47%, P < 0.001; tumor weight: reduced by 58%, P < 0.01)." (PMID 40533863, 2025). "Subsequently, tumor tissues from the mice were analyzed using western blot to assess the expression changes of NOLC1, stemness markers, and proteins in the NOTCH signaling pathway." (PMID 39789998, 2025). "H&E staining revealed that the NOLC1-knockdown groups presented a larger necrotic area in the tumor tissues after Cis treatment." (PMID 40864495, 2025). "This work demonstrated that the NOTCH pathway acted as a mediating factor in the promotion of tumor cells' stemness when NOLC1 expression in LUAD was elevated." (PMID 39789998, 2025). "Knockdown of NOLC1 reprogrammed the tumor microenvironment after cisplatin (Cis) and anti-programmed cell death-1 (anti-PD-1) combination therapy." (PMID 40864495, 2025). "More importantly, NOLC1 is involved in tumor genesis and development through chemokine responses, drug transport, and positive and negative regulation of Wnt signaling pathways." (PMID 37670166, 2023). "In this study, our data provided further evidence that NOLC1 expression levels were overexpressed in ESCC tissues compared to normal adjacent tumor and correlated with poor prognosis." (PMID 34046062, 2021). "Increasing evidences suggested that NOLC1 played a tumor suppressive role by inducing cell-cycle arrest." (PMID 33767130, 2021). "In this study, we found that NOLC1 knockdown could transform the chemoresistance tumor environment to a sensitive state." (PMID 40864495, 2025). "Furthermore, the upregulation of circ-NOLC1 expression significantly inhibited the proliferation, migration, and invasion of CC cells while promoting the apoptosis rate of tumor cells." (PMID 40533863, 2025). "In nude mice with subcutaneous tumors, circ-NOLC1 downregulation decreased tumor growth." (PMID 33483472, 2021). "Nude mice xenograft assays demonstrated that the tumorigenicity was inhibited in mice injected with circ-NOLC1-downregulated A2780 cells (p < 0.05) compared with that in the control group, and the tumor volumes were smaller in the circ-NOLC1 downregulation group (p < 0.05)." (PMID 33483472, 2021). "At 35 days after inoculation, the mice were killed, and the mice injected with HepG2‐NOLC1 and SMMC7721‐NOLC1 cells displayed a larger burden, which indicated that NOLC1 may participate in HCC tumor proliferation." (PMID 28493459, 2017). "The methylation of these genes was also examined using the GSCALite database, and we discovered that NOLC1 was hypomethylated based on methylation difference between tumor and normal samples in COAD, which may be connected to the high level of this gene expression in COAD." (PMID 37604903, 2023).
tumor (continued). "Nucleolar and coiled-body phosphoprotein 1 (NOLC1) expression is increased in HCC tissue, and its reduction inhibits rRNA processing, proliferation of HCC cells, and tumor growth." (PMID 40521004, 2025). "This provides a strong complement to the mechanism of NOTCH pathway activation in LUAD, suggesting that targeting the FOXA1/NOLC1 axis is an effective way to regulate LUAD NOTCH pathway and suppress tumor cell stemness." (PMID 39789998, 2025). "CSIG knockdown increased the expression of NOLC1 in HCC cell lines, and its overexpression repressed the proliferation of HCC cell lines and affected HCC tumor growth in nude mice." (PMID 28493459, 2017). "Furthermore, the silence of NOLC1 promoted ferroptosis-induced immunogenic cell death (ICD) and reprogrammed the immunosuppressive tumor microenvironment, thereby increasing sensitivity to anti-programmed cell death-1 (PD-1) therapy plus Cis." (PMID 40864495, 2025). "In addition, the relationship between NOLC1 and CD274, PDCD1, and PDCD1LG2, which are important immune checkpoints for tumor immune escape, was also explored." (PMID 37670166, 2023). "The tumor-promoting effect of circ-NOLC1 was inhibited by knockdown of ESRP1, CDK1, or RhoA expression in circ-NOLC1-overexpressing cells, which might act by modulating RhoA and CDK1 expression." (PMID 33483472, 2021). "Furthermore, the identification of this ceRNA mechanism not only offers novel insights into the progression of CC but also underscores circ-NOLC1 as a potential prognostic biomarker and therapeutic target for restoring PALM-dependent tumor-suppressive functions in CC." (PMID 40533863, 2025). "In addition, the tumor-promoting effect of circ-NOLC1 was reduced after ESRP1, CDK1, or RhoA knockdown in circ-NOLC1-overexpressing cells, thus we hypothesized that circ-NOLC1 might function as an oncogene through binding and modulating ESRP1, CDK1, and RhoA levels." (PMID 33483472, 2021).